DKK3 (dickkopf Wnt signaling pathway inhibitor 3)
Diseases named in the same sentence as DKK3 in open-access papers (continued):
Sharing a sentence is not in itself a finding about the gene and the disease.
osteosarcoma (18 papers, 2004 to 2025). A usually aggressive malignant bone-forming mesenchymal neoplasm, predominantly affecting adolescents and young adults. "Contradictory to this, Dkk3 is reported to function as an inhibitor of Wnt signaling, either by associating with bTrCP and blocking β–catenin from entering the nucleus (as seen in HeLa cells), or by increasing the localisation of β–catenin in the cell membrane, as seen in osteosarcoma cells." (PMID 25029272, 2014). "Significantly down-regulated DKK3 expression was identified in human osteosarcoma tissues and cells." (PMID 34326690, 2021). "The decreased DKK3 expression was further confirmed in osteosarcoma cells (143B, U-2 OS, MNNG, and Saos-2) than in hFOB1.19 cells by RT-qPCR and Western blot assays." (PMID 34326690, 2021). "The aim of our current work was to explore oncogenic function of miR-214-3p/DKK3/Wnt/β-catenin axis in osteosarcoma." (PMID 34326690, 2021). "Then the anti-osteosarcoma effects of cantharidin both in vivo and in vitro, as well as the specific contribution of miR-214-3p/DKK3/GSK-3β/β-catenin/LEF1 axis were further investigated." (PMID 34326690, 2021). "Cantharidin inhibits osteosarcoma cell proliferation and metastasis via specific down-regulation of miR-214-3p to prevent DKK3 from being degraded." (PMID 34326690, 2021). "We showed that Dkk-3 downregulates β-catenin nuclear translocation in osteosarcoma cells resulting in inhibition of downstream Wnt-mediated lymphoid enhancer factor/TCF activation." (PMID 23476112, 2013). "As seen in other cancer cell lines, Dkk-3 protein expression was downregulated with varying degree in all osteosarcoma cell lines." (PMID 23476112, 2013). "In this study, we continued to focus on the effects of Dkk-3 in vitro and in vivo to assess its ability to decrease tumor progression in osteosarcoma and elucidated the potential molecular mechanism." (PMID 23476112, 2013). "This suggests that cantharidin may be a prospective natural drug candidate for osteosarcoma treatment by targeting the miR-214-3p/DKK3/GSK-3β/β-catenin/LEF1 axis." (PMID 34326690, 2021). "Therefore, inhibiting Wnt/β-catenin signaling activity with DKK3 via down-regulating miR-214-3p is a promising strategy to develop novel treatments for osteosarcoma patients." (PMID 34326690, 2021). "To evidence this hypothesis, we first evaluated mRNA expression of DKK3 by RT-qPCR in paired human osteosarcoma (Tumor) and paracancerous normal tissues (Control) from 3 patients." (PMID 34326690, 2021). "Moreover, an endogenous inhibitor of the Wnt pathway, Dickkopf-3 (Dkk3), affects intracellular ß-catenin resulting in suppression of metastasis and invasion in osteosarcoma cells." (PMID 34671398, 2021). "The results revealed a significantly decreased DKK3 expression in osteosarcoma tissues." (PMID 34326690, 2021). "DKK3 has also been reported to suppress the infiltration and metastasis of osteosarcoma." (PMID 31698687, 2019). "However, the miR-214-3p/DKK3/GSK-3β/β-catenin/LEF1 axis related pharmacological mechanism of cantharidin on osteosarcoma remains unknown." (PMID 34326690, 2021). "For instance, in osteosarcoma, CTD downregulated miR-214-3p and upregulated dickkopf-3 (DKK3), leading to reduced nuclear translocation of β-catenin, thereby inhibiting cell proliferation and metastasis while enhancing apoptosis." (PMID 41339928, 2025). "Our results showed that cantharidin up-regulated DKK3, decreased miR-214-3p, p-GSK-3β, active β-catenin, nuclear β-catenin and LEF1 expressions in osteosarcoma cells." (PMID 34326690, 2021). "Up-regulated miR-214-3p promoted proliferation and migration, while suppressed apoptosis of osteosarcoma cells by increasing β-catenin nuclear translocation and LEF1 translation via degradation of DKK3." (PMID 34326690, 2021).
osteosarcoma (continued). "Therefore, we hypothesized that up-regulating DKK3 via down-regulating miR-214-3p will achieve an inhibitory outcome on Wnt/β-catenin signaling activity, which will be a promising strategy to develop novel treatments for osteosarcoma patients." (PMID 34326690, 2021). "More specifically, previous studies have shown that downregulating the Wnt pathway by transfecting Dkk-3 and dominant-negative LRP5 into osteosarcoma cells significantly reduced invasion capacity and cell motility potentially by recruiting β-catenin to the cell surface to promote cell-cell adhesion." (PMID 23125530, 2012). "Together, these data suggest that Dkk-3 has a negative impact on the progression of osteosarcoma." (PMID 23476112, 2013). "However, whether the miR-214-3p/DKK3/Wnt/β-catenin axis involves in osteosarcoma progression has not been reported." (PMID 34326690, 2021).
atherosclerosis (17 papers, 2017 to 2025). A disease characterized by the build-up of fatty material and calcium deposition in the arterial wall resulting in partial or complete occlusion of the arterial lumen. "In a cohort derived from the general population, plasma levels of DKK3 were inversely associated with atherosclerosis development." (PMID 33883651, 2021). "In ApoE-deficient mice, the expression of DKK3 was involved in the pathogenesis of atherosclerosis via the Wnt/β-catenin pathway." (PMID 34631806, 2021). "In the present study, we found a U-shaped association between serum Dkk-3 and poor prognosis, which was concordant with the observed complex effects of Dkk-3 on the atherosclerosis." (PMID 31918729, 2020). "Overall, strong evidence exists of an inverse association between DKK3 level and both early and advanced stages of atherosclerosis." (PMID 28674110, 2017). "It was demonstrated that DKK3 deficiency accelerated atherosclerosis and delayed reendothelialization with consequently exacerbated neointima formation." (PMID 28674110, 2017). "DKK3-deficient mice were crossed with apolipoprotein E-/- mice to evaluate atherosclerosis development and vessel injury-induced neointimal formation." (PMID 28674110, 2017). "Hence, DKK-3 has recently gained attention as a potential biomarker for cardiovascular disease, particularly in assessing atherosclerosis risk." (PMID 41356214, 2025). "Dickkopf-3 (Dkk-3) is implicated in the progression of atherosclerosis." (PMID 31918729, 2020). "In the prospective population-based Bruneck Study, the level of plasma DKK3 was inversely related to carotid artery intima-media thickness and 5-year progression of carotid atherosclerosis independently from standard risk factors for atherosclerosis." (PMID 28674110, 2017). "In contrast, as an important regulator of cell fate determination, Dkk-3 had a certain role in the protection against atherosclerosis involving endothelial migration and repair." (PMID 31918729, 2020). "This study suggested a protective role of Dkk-3 in the context of atherosclerosis progression by inducing endothelial migration and post-injury repair." (PMID 33081636, 2020). "On the other hand, since it is an essential regulator of cell fate determination, Dkk3 was also mentioned to have a protective function against atherosclerosis." (PMID 33317034, 2020). "Conversely, as an important regulator of cell fate determination, Dkk-3 was also reported to have certain protective roles against atherosclerosis." (PMID 31918729, 2020). "Dkk3 (dickkopf-3) is involved in vascular remodeling, for example, atherosclerosis, vascular injury-induced stenosis, and plaque stability." (PMID 29980568, 2018). "In the present study, we take advantage of relevant human samples, transgenic animals, and in vitro cell biology models to elucidate the potential impact of DKK3 in atherosclerosis." (PMID 28674110, 2017). "In humans, we observed an inverse correlation between blood DKK3 level and development of atherosclerosis." (PMID 28674110, 2017). "This study provides the evidence for a role of DKK3 in the protection against atherosclerosis involving endothelial migration and repair, with great therapeutic potential implications against atherosclerosis." (PMID 28674110, 2017). "Among the DKK proteins, DKK-3 has recently emerged as an important player in the development of atherosclerotic plaque and participates in different stages of atherosclerosis, from endothelial dysfunction to lipid deposit and from initial inflammation to plaque formation." (PMID 41356214, 2025). "Moreover, DKK3 ablation in mice was found to prevent atherosclerosis development by alleviation of inflammatory response and the reduction of the level of MMPs." (PMID 40948935, 2025). "In addition, in animal studies, the severity of atherosclerosis in large vessels was negatively correlated with DKK3 expression." (PMID 38678874, 2024).
atherosclerosis (continued). "However, recent studies have found that DKK3 can prevent cardiac dysfunction and ventricular remodeling after myocardial infarction, and can antagonize the atherosclerosis process by regulating inflammatory response and Wnt/β pathway." (PMID 38678874, 2024). "Interestingly, DKK3 was reported to be involved in inhibition of hepatic steatosis, prevention of myocardial infarction, and anti-atherosclerosis." (PMID 36410795, 2023). "Multiple studies described the role of DKK3 in atherosclerosis development using atherosclerosis-prone apolipoprotein E-deficient (ApoE−/−) mice, but these studies showed opposing results, either suggesting accelerated or reduced atherosclerosis in DKK3−/− mice." (PMID 33883651, 2021). "As an antagonist of Wnt/β-catenin pathway, the overexpression of Dkk-3 could accelerate the atherosclerotic process and resulted in detrimental outcomes of atherosclerosis through inhibiting this pathway." (PMID 31918729, 2020). "Some studies showed that Dkk-3 could play important roles in the development and progression of atherosclerosis." (PMID 31918729, 2020). "Plasma Dkk-3 concentration was inversely related to carotid artery intima-media thickness, and Dkk-3 could promote re-endothelialization after atherosclerosis or artery injury." (PMID 31918729, 2020). "Various in vivo studies have reported on effects of DKK3 on atherosclerosis development." (PMID 32345717, 2020). "Given the important regulating roles of Dkk-3 in the process of atherosclerosis, it is of clinical interest to investigate whether serum Dkk-3 can provide additional prognostic value for ischemic stroke." (PMID 31918729, 2020). "Dickkopf-related protein 3 (DKK3) is a secreted protein that is involved in the regulation of cardiac remodeling and vascular smooth muscle cell differentiation, but little is known about its role in atherosclerosis." (PMID 28674110, 2017). "In addition, we utilized genetic knockout mouse models combined with apolipoprotein E (ApoE)-/- mouse to assess the effects of DKK3 on atherosclerosis, reendothelialization, and neointima formation after femoral artery injury." (PMID 28674110, 2017). "In summary, in the current study, we have provided the first evidence that DKK3 potentially confers protection against atherosclerosis in human subjects and established that DKK3 affects atherosclerosis progression and neointimal formation in mouse models by influencing reendothelialization." (PMID 28674110, 2017). "Our findings support the notion that the lower levels of DKK3, which were found in the blood of patients with atherosclerosis, could be explained by lower DKK3 release because of endothelial dysfunction." (PMID 28674110, 2017). "The data derived from experimental models provide direct evidence that DKK3 could act as a chemokine-like protein in endothelial migration and thus be protective of atherosclerosis." (PMID 28674110, 2017). "After being released into the blood, DKK3 may exert its effect on endothelial cells and subsequently the development of atherosclerosis." (PMID 28674110, 2017). "Thus, it seems that DKK3 exerts its effect on endothelial functions related to atherosclerosis independently of other members of DKK family proteins." (PMID 28674110, 2017). "Although not yet investigated in the context of periodontitis, DKK-3 has gained recognition as a key biomarker in cardiovascular diseases, particularly atherosclerosis." (PMID 41356214, 2025). "DKK3 has been found to inhibit inflammation via the non-canonical Wnt signaling pathway in a model of atherosclerosis." (PMID 35658977, 2022). "DKK3 has been reported to inhibit inflammation through the noncanonical Wnt signaling pathway in a model of atherosclerosis." (PMID 32331523, 2020). "Moreover, the absence of DKK3 decreased the level of MMPs and contributed to the reduction of atherosclerosis." (PMID 40948935, 2025).
atherosclerosis (continued). "Dkk-3 could promote re-endothelialization and reduced neointima formation after atherosclerosis or artery injury, and the absence of Dkk-3 was also related to incident carotid atherosclerosis and stenosis during 5-year follow-up." (PMID 31918729, 2020).
chronic kidney disease (17 papers, 2017 to 2025). Impairment of the renal function secondary to chronic kidney damage persisting for three or more months. "Dickkopf 3 (DKK3), a profibrotic glycoprotein, has recently been identified as a biomarker for estimating the risk of rapid eGFR loss in patients with chronic kidney disease." (PMID 39685912, 2024). "In detail, DKK3 seems to interfere with the Wnt/β-catenin pathway, which is known to be implicated in the progression of chronic kidney disease (CKD)." (PMID 35683365, 2022). "This will help to determine whether DKK3 can be used as a reliable early marker to identify children at risk of developing chronic kidney disease." (PMID 39904897, 2025). "Serum Dkk-3 is also a potential biomarker for tissue fibrosis for lymphatic nephritis associated with systemic lupus erythematous disease (SLE), and increased urinary Dkk-3 can identify patients with chronic kidney disease who are at risk for loss of kidney function." (PMID 36497305, 2022). "DKK3 levels were associated with prevalent chronic kidney diseases (OR: 4.31 [C.I. 2.01–6.61] per DKK3 doubling, p < 0.01), higher chronicity index at biopsy (1.75 [1.51–2.77] per DKK3 doubling, p < 0.01), and flares rate (OR: 1.45 [C.I. 1.1–5.71] per DKK3 doubling, p < 0.044)." (PMID 35683365, 2022). "Urinary DKK3 serves as a kidney-specific biomarker associated with tubular stress and fibrosis, whereas plasma DKK3 levels integrate signals from various tissues, reducing its specificity for chronic kidney disease (CKD)." (PMID 40568561, 2025). "The levels of DKK-3, a stress-induced tubular epithelia-derived profibrotic glycoprotein, are significantly elevated in association with a higher degree of tubulointerstitial fibrosis in different glomerular and tubulointerstitial diseases and they were related to progressive chronic kidney disease." (PMID 37020541, 2023). "Recently Dkk3 was described as a biomarker of tubular cell injury and a tool that may estimate the risk of chronic kidney disease (CKD) progression." (PMID 37510820, 2023). "For example, Dkk3 was secreted in the urine of mice in stress induced tubular atrophy and fibrosis in chronic kidney diseases." (PMID 29717119, 2018). "We have determined urinary DKK3 concentrations in two different age groups: children/adolescents and adults, both with mixed etiologies of their chronic renal diseases." (PMID 28685176, 2017). "Whereas, in the context of chronic kidney disease, Dickkopf 3 has been recognized as a marker to identify patients at risk for a progressive loss of kidney function, to date, the impact of DKK3 after transplantation has not yet been analyzed." (PMID 35646976, 2022). "Thus, it was speculated that increased urinary DKK3 concentrations could indicate a higher risk of progression of chronic kidney disease (CKD)." (PMID 33275197, 2021). "Background and Objectives: Urinary levels of dickkopf-3 (DKK-3) are associated with poor renal survival in patients with non-dialytic chronic kidney disease." (PMID 34207077, 2021). "Also, with increasing DKK3 quintiles, a higher prevalence of hypertension, chronic kidney disease (CKD) and cardiovascular disease (CVD) was observed." (PMID 33883651, 2021). "Based on our immunologic studies with DKK3 in the skin, brain, and the lymphopoietic system, we have postulated that DKK3 might demonstrate immunosuppressive and fibrogenic actions in chronic renal disease." (PMID 28685176, 2017). "We review the biological role of DKK3 as an agonist in chronic kidney disease (CKD) and autosomal dominant polycystic kidney disease (ADPKD) and as an antagonist in idiopathic membranous nephropathy (IMN)." (PMID 33391006, 2020). "In a mouse model of chronic kidney disease (CKD), knockout of the DKK3 gene alleviated renal fibrosis." (PMID 40406118, 2025). "Dickkopf-3 (DKK3) is an emerging biomarker for cardiovascular disease (CVD) and chronic kidney disease (CKD)." (PMID 33883651, 2021).
chronic kidney disease (continued). "It was concluded that urinary DKK3 was an independent predictor of contrast-induced-AKI even in the absence of overt chronic kidney disease." (PMID 40332103, 2025). "Urinary DKK3 is an independent predictor of CI-AKI even in the absence of overt chronic kidney disease (CKD)." (PMID 33275197, 2021).
cervical carcinoma (14 papers, 2014 to 2023). A carcinoma arising from either the exocervical squamous epithelium or the endocervical glandular epithelium. "Association between DKK3 expression and clinicopathological characteristics of cervical cancer patients." (PMID 35924156, 2022). "The loss of tumor suppressor DKK3 was important for invasion of cervical cancer." (PMID 30970615, 2019). "The Dickkopf 3 (Dkk3) protein was significantly downregulated and showed a strong regulation of β-catenin in cervical cancer cells." (PMID 32758292, 2020). "Two studies reported that down-regulation of DKK3 was bound up with poor clinical prognosis of cervical cancer, while up-regulation of DKK3 inhibited the proliferation of cervical cancer cells." (PMID 30926679, 2019). "Dkk3 has also been reported to inhibit TGFβ signaling in both Xenopus and several mammalian cell types such as prostate epithelial cells, cervical cancers, and cartilage cells." (PMID 29717119, 2018). "Interestingly, the targeted relationship between miR-92a and DKK3 has also been demonstrated in cervical cancer and neuroblastoma." (PMID 30926679, 2019). "miR-92a-5p is thought to induce its effects by targeting essential molecules in the cell cycle, including Retinoblastoma (RB), Dickkopfrelated protein 3 (DKK3) and FBXW7 mRNA and then, promotes cell proliferation and invasion in cervical cancer." (PMID 33906322, 2021). "PAX6 knockdown did not influence DKK3 expression in the HeLa (human cervix carcinoma) or U-87 (human glioblastoma) cell lines (results not shown)." (PMID 25029272, 2014).